PKMYT1AR (PKMYT1 associated lncRNA)
Gene: Long non-coding RNA gene on chromosome 19 (57,477,308 to 57,482,996, forward strand). Ensembl gene ENSG00000268266.
Diseases named in the same sentence as PKMYT1AR in open-access papers:
PKMYT1AR is named in the same sentence as 4 diseases in open-access papers, as found by Europe PMC text mining. Sharing a sentence is not in itself a finding about the gene and the disease. The quoted sentences say what the papers report.
lung carcinoma (2 papers, 2021 to 2025). "Our previous studies found that ASOs targeting PKMYT1AR could significantly inhibit the self-renewal capability of lung cancer stem cells and suppress lung tumor growth." (PMID 40860186, 2025). "Except for PKMYT1AR, the other two lncRNAs have been well characterized in lung cancer." (PMID 34856993, 2021).
tumor (3 papers, 2021 to 2024). "Furthermore, the reduced cell proliferation, colony formation and migration abilities of tumor cells caused by PKMYT1AR knockdown can be overcame by miR-485-5p inhibitor overexpression, strongly supporting the specific role of PKMYT1AR/ miR-485-5p axis." (PMID 34856993, 2021). "Next, we found that PKMYT1AR promotes the proliferation, migration, stemness maintenance and xenograft tumor formation abilities of NSCLC tumor cells." (PMID 34856993, 2021). "Most importantly, the reciprocal rescue experiment results based on the signaling axis of PKMYT1AR/miR-485-5p/PKMYT1 using tumor sphere formation assay, strongly support the specific role in NSCLC cancer stem cells." (PMID 34856993, 2021). "We show that PKMYT1AR high expression correlates with worse clinical outcome, and knockdown of PKMYT1AR inhibits tumor cell proliferation, migration and xenograft tumor formation abilities." (PMID 34856993, 2021). "The cell proliferation marker Ki67 and cellular apoptosis marker cleaved caspase 3 (CC3) in the xenograft tumors were then examined by immunohistochemical (IHC) staining, and we verified that PKMYT1AR knockdown inhibited tumor cell proliferation but promoted cellular apoptosis in vivo." (PMID 34856993, 2021). "Next, we used wound healing and trans-well assays to test whether PKMYT1AR regulates tumor cell migration, and the results showed that the tumor cell migration ability was dramatically repressed in PKMYT1AR knockdown cells compared with control group." (PMID 34856993, 2021). "To further define the functional role of PKMYT1AR regulating NSCLC progression in vivo, we performed the xenograft tumor formation assay." (PMID 34856993, 2021). "In view of PKMYT1AR function in NSCLC, the authors also targeted it in vitro and in tumor xenografts, showing that its inhibition through ASOs can efficiently impair tumor stem features, as self-renewal, and the expression of stem cell markers, as CD44 and SOX2." (PMID 36768150, 2023).
cancer (2 papers, 2021 to 2024). A tumor composed of atypical neoplastic, often pleomorphic cells that invade other tissues. "To uncover the non-coding RNAs critical for cancer stem cell maintenance, by applying multiple web source available datasets, we were able to identify lncRNA PKMYT1AR as an oncogenic factor promoting NSCLC progression." (PMID 34856993, 2021). "Our findings reveal that PKMYT1AR/miR-485-5p /PKMYT1 axis is important for cancer stem cell maintenance and NSCLC progression both in vitro and in vivo, suggesting that PKMYT1AR, miR-485-5p or PKMYT1 could be used as novel therapeutic targets in the future." (PMID 34856993, 2021).
PKMYT1AR also shares sentences with these, for which no sentence is quoted: non-small cell lung carcinoma (2 papers).